HIF3A (hypoxia inducible factor 3 subunit alpha)
Diseases named in the same sentence as HIF3A in open-access papers (continued):
Sharing a sentence is not in itself a finding about the gene and the disease.
hepatocellular carcinoma (4 papers, 2018 to 2023). A malignant tumor that arises from hepatocytes. "For example, TIMP2 (tissue inhibitor of metalloproteinases 2) blockade by HIF-1α/miR-210/HIF-3α feed circuit often plays a significantly role in regulating hepatocellular carcinoma (HCC) metastasis, which is regard as associated with poor prognostic effects." (PMID 33109235, 2020). "Several reports have indicated how hypoxia-induced miRNAs regulated the switch between HIF-1α and HIF-3α in human endothelial cells and how their regulatory feedback circuit enhanced tumor metastasis in hepatocellular carcinoma." (PMID 36277475, 2022). "The study in hepatocellular carcinoma demonstrated that the HIF-1α/miR-210/HIF-3α feedback circuit plays a regulatory role in TIMP2 suppression." (PMID 29953500, 2018). "Interestingly, in hepatocellular carcinoma, the overexpression of HIF-2α promoted HIF-3α expression, while HIF-1α remained unmodified." (PMID 37833987, 2023). "In samples collected from patients suffering hepatic carcinoma, HIF-3α was shown to be upregulated in 46% of the samples; nonetheless, it was also observed to be downregulated in another 42% of cases." (PMID 37833987, 2023).
prostate carcinoma (4 papers, 2014 to 2020). A carcinoma that arises from epithelial cells of the prostate gland. "HIF3A (hypoxia inducible factor 3 subunit alpha) is another gene that has been linked to prostate cancer." (PMID 32252623, 2020). "For example, in prostate cancer, HIF-3α gene has been found hypermethylated compared to healthy tissue from the same patient and this promotes carcinogenesis." (PMID 31234835, 2019). "Recent reports illustrated that methylation of HIF3α could be an early event in prostate cancer development." (PMID 24801981, 2014).
renal cell carcinoma (4 papers, 2014 to 2024). "In the human renal cell carcinoma cells and osteosarcoma cells, overexpressed HIF3A evidently inhibited HIF1-induced VEGF expression." (PMID 25340332, 2014).
alveolar cell carcinoma (3 papers, 2016 to 2021). "The unbiased discovery of the AHR pathway as well as pathways involved in hypoxia (HIF3A) and mucosa-mediated clearance of lung airways (FOXJ1), demonstrates the ability of SEPIRA to identify early and potentially causal pathways in lung cancer development." (PMID 29262847, 2017). "However, the specific role of hypoxia‐inducible factor 3 alpha (HIF3A) in non‐small cell lung cancer (NSCLC) remains controversial." (PMID 34245041, 2021).
Alzheimer disease (3 papers, 2023 to 2025). A progressive, neurodegenerative disease characterized by loss of function and death of nerve cells in several areas of the brain leading to loss of cognitive function such as memory and language. "Non-gonosomal genes that were differentially regulated between sexes included an upregulation of NRXN1 in female oligodendrocytes, which has previously been linked to Alzheimer’s disease and multiple sclerosis, and of HIF3A in female OPCs which is related to oxidative stress." (PMID 37217978, 2023). "This study demonstrates that circadian disruption exacerbates neuroinflammation, oxidative stress, and organ damage in Alzheimer’s disease, while Hif3α inhibition and BLFs offer partial protection." (PMID 40243952, 2025). "Similarly, our transcriptome sequencing results showed a significant increase in Hif3α mRNA levels in both normal and Alzheimer’s disease (AD) mice following circadian rhythm disruption (p < 0.001)." (PMID 40243952, 2025).
Anxiety (3 papers, 2022 to 2024). Intense feelings of nervousness, tension, or panic often arise in response to interpersonal stresses. "A recent study revealed HIF3A occupancy at transcriptional control regions of critical genes implicated in regulating alcohol and anxiety-related comorbid behaviors, such as neuropeptide Y (Npy) and activity-regulated cytoskeletal associated protein (Arc)." (PMID 36089615, 2022). "We investigated whether induction of Hif3a mRNA in the adult male CeA is involved in the ethanol-induced anxiolysis, as this brain region is implicated in anxiety and alcohol-related behaviors." (PMID 36089615, 2022). "Hif3a is induced following acute ethanol, which is associated with anxiolytic-like behavior, and decreased during withdrawal after chronic ethanol exposure, which is associated with increased anxiety-like behavior." (PMID 36089615, 2022). "Another study found that HIF3A could be epigenetically induced in the amygdala in animal models by acute alcohol exposure, and its epigenetic reprogramming was associated with the anti-anxiety effect of acute alcohol exposure." (PMID 38177348, 2024). "We used an established animal model of alcohol dependence, wherein rats exhibit anxiety-like behaviors during withdrawal following chronic ethanol exposure, and measured Hif3a expression in these amygdala tissues." (PMID 36089615, 2022). "This is mechanistically supported by the fact that infusion of Hif3a siRNA into the CeA provoked anxiety-like behaviors in alcohol naïve male control rats." (PMID 36089615, 2022). "AUD comorbid with anxiety has a complex multifactorial etiology, and these data make a compelling argument to target HIF3A signaling in the amygdala for the development of pharmacological interventions in the treatment of AUD." (PMID 36089615, 2022). "We identified an epigenetic target, Hif3a, in the amygdala that regulates anxiety-related behaviors after ethanol exposure." (PMID 36089615, 2022). "Our explanation was alcohol could play an anti‐anxiety role by regulating the expression of the Hif3a gene in the amygdala, thus alleviating fatigue." (PMID 38659395, 2024). "Interestingly, Hif3a siRNA infusion in ethanol-naïve control rats decreased Hif3a mRNA levels in the amygdala and provoked anxiety-like behaviors." (PMID 36089615, 2022). "Interestingly, knockdown of Hif3a in the CeA induced anxiety-like behaviors in ethanol-naïve control rats, mimicking the ethanol withdrawal effects on these measures." (PMID 36089615, 2022). "The differential reduction in anxiety by Hif3a siRNA in control and alcohol-treated animals may be related to differential baseline anxiety levels." (PMID 36089615, 2022).
breast carcinoma (3 papers, 2020 to 2025). "In contrast, in colorectal cancer, lower CUL1 expression correlates with better outcomes, while in breast cancer, reduced HIF3A levels indicate a more favorable prognosis." (PMID 40524221, 2025). "A few studies have shown that the gene expression of HIF3A was downregulated in breast cancer and non-small cell lung cancer." (PMID 35652069, 2022). "For example, hypoxia-inducible factor 3-alpha (HIF3A) is globally downregulated in cancers especially in breast cancer." (PMID 33299416, 2020).
colorectal cancer (3 papers, 2020 to 2025). A primary or metastatic malignant neoplasm that affects the colon or rectum. "Hypermethylation of hypoxia-inducible factor 3 Subunit Alpha (HIF-3α) in obese women has been associated with breast, oesophageal, thyroid and colorectal cancer." (PMID 37233716, 2023). "HIF3A promotes colorectal cancer cell growth through non-canonical transcription-independent mechanisms." (PMID 32296392, 2020).
diabetes (3 papers, 2020 to 2025). "In the present study, B12 modulated several core clock genes (Bmal1, Cry1, Cry2, Per1, Per3), while other genes were primarily affected by diabetes (Bhlhe40, Hif3a, and Nr1d1)." (PMID 41463345, 2025).
gastric cancer (3 papers, 2017 to 2025). A primary or metastatic malignant neoplasm involving the stomach. "Transcriptome analysis of four high EBV+ primary gastric cancers from the TCGA cohort indicated that HIF-1α mRNA was, on average, 2.9-fold more abundant than HIF-2α mRNA (range 1.9-fold to 4.9-fold), with HIF-3α mRNA undetectable above background level." (PMID 28617871, 2017). "In the existing research, OGFRP1 was investigated to enhance the growth of gastric cancer cells and inhibit cell death and sensitivity to radiation by controlling the miR-149-5p/MAP3K3 pathway, which has been demonstrated to play a similar role in choriocarcinoma through the miR-4731-5p/HIF3A axis." (PMID 39352634, 2025).
metabolic syndrome (3 papers, 2018 to 2022). A cluster of metabolic risk factors for CARDIOVASCULAR DISEASES and TYPE 2 DIABETES MELLITUS. "In humans with high BMI, often associated with metabolic syndrome characterized by chronic inflammation, is HIF3α silenced pointing out a role in metabolic surveillance?" (PMID 29643458, 2018). "Moreover, increased methylation of HIF3α in umbilical cord tissue was associated with higher gestational weight gain, infant birth weight and adiposity, suggesting that HIF3α methylation may be a potential biomarker from metabolic syndrome." (PMID 36992770, 2022).
neuroblastoma (3 papers, 2012 to 2020). Neuroblastoma (NB) is the most common solid, extracranial childhood tumor. "Consequently, we do not consider HIF3A to be a particularly important player in neuroblastoma and will not include the gene or its protein product in our later discussions in this review." (PMID 29032465, 2018).
non-small cell lung carcinoma (3 papers, 2020 to 2023). A group of at least three distinct histological types of lung cancer, including non-small cell squamous cell carcinoma, adenocarcinoma, and large cell carcinoma. "And some research has demonstrated a positive role for HIF-3α in non-small cell lung cancer (NSCLC)." (PMID 37886168, 2023). "Over-expression of miR-300 inhibited proliferation, invasion and migration of non-small cell lung cancer cells in vitro, and tumor growth in vivo by downregulating HIF3A expression." (PMID 32296392, 2020).
pancreatic cancer (3 papers, 2020 to 2023). "There are few studies on HIF-3α, and it has been reported that increased HIF-3α expression is associated with pancreatic cancer metastasis and ovarian cancer progression." (PMID 37692844, 2023). "Furthermore, HIF-3α has been implicated in the progression of pancreatic cancer by directly binding the promoters of RHOC and ROCK1 and transactivating the RhoC-ROCK1 pathway in cancer cells that overexpress HIF3A." (PMID 31768607, 2020). "This is consistent with a recent study showing that HIF-3α promotes pancreatic cancer cell invasion and migration under both normoxia and hypoxia." (PMID 38020884, 2023).
renal carcinoma (3 papers, 2017 to 2023). A carcinoma arising from the epithelium of the renal parenchyma or the renal pelvis. "In contrast, HIF-3α was largely found to co-localize with HIF-1α in human renal carcinoma cells, but the regulation of HIF-3α remains elusive." (PMID 37833987, 2023). "The present study has shown for the first time that Zn2+ induces expression of HIF1α and HIF2α but not HIF3α in the renal cancer cell line ACHN and the immortalized normal tubular cell line HK-2." (PMID 28686686, 2017).
choriocarcinoma (2 papers, 2022 to 2025). An aggressive malignant tumor arising from trophoblastic cells. "Interference of miR-4731-5p promoted the growth, migration, and invasion of choriocarcinoma by targeting HIF3A as well." (PMID 35342398, 2022).
clear cell renal cell carcinoma (2 papers, 2021 to 2024). "Results from Cox regression analysis of factors important for cancer-specific survival in 149 patients with clear cell renal cell carcinoma, adjusted for age, gender, tumor size (mm), tumor grade, tumor stage, and HIF-1α, HIF-2α, and HIF-3α nuclear and cytoplasmic expression levels, respectively." (PMID 38571885, 2024).
COVID-19 (2 papers, 2023 to 2025). A disease caused by infection with severe acute respiratory syndrome coronavirus 2. "In our study, we assessed the expression of various HIF isoforms (HIF-1α, HIF-2α, HIF-3α) and found that the expression of all subunits significantly increased in COVID-19 patients." (PMID 40702494, 2025). "Although studies on HIF-3α regulation in COVID-19 are still in their early stages and require further exploration, they offer potential for developing novel therapeutic strategies for severe disease." (PMID 40702494, 2025). "In 2021, HIF3A was found to be downregulated within the frontal cortices of patients with COVID-19." (PMID 37109540, 2023). "In severe COVID-19, we observed significant imbalances in HIF-1α/HIF-3α and HIF-2α/HIF-3α ratios, suggesting a breakdown in hypoxic adaptation and the onset of pathological inflammation." (PMID 40702494, 2025). "In patients with mild and moderate COVID-19, HIF-2α expression increased the most (6-fold and 10.6-fold relative to controls), followed by HIF-1α (4.3-fold and 8.2-fold), and to a lesser extent, HIF-3α (6.2-fold and 7.1-fold)." (PMID 40702494, 2025). "Simultaneous measurement of HIF-1α, HIF-3α, and HIF1-AS1 expression may serve as a reliable model for early prediction of COVID-19 severity, especially in patients with comorbidities such as diabetes and obesity." (PMID 40702494, 2025).
glioma (2 papers, 2015 to 2025). A benign or malignant brain and spinal cord tumor that arises from glial cells (astrocytes, oligodendrocytes, ependymal cells). "Similarly, HIF3A (Hypoxia Inducible Factor 3 Alpha) likely contributes to the hypoxic adaptation that characterizes aggressive gliomas, promoting treatment resistance and accelerated disease progression." (PMID 41356219, 2025). "Five genes (KIF5C, LINC00632, B4GALNT3, HIF3A, and RAD51L3-RFFL) show significant differential expression between primary and recurrent tumors, with four having established functional roles in glioma pathobiology." (PMID 41356219, 2025). "The identification of five genes (KIF5C, LINC00632, B4GALNT3, HIF3A, and RAD51L3-RFFL) with differential expression between primary and recurrent tumors provides critical insight into the molecular mechanisms driving recurrence, the key challenge in the management of IDH wild-type glioma." (PMID 41356219, 2025).
Hyperglycemia (2 papers, 2012 to 2021). An increased concentration of glucose in the blood. "Moreover, DMDD treatment inhibited hyperglycemia-induced apoptosis through inhibiting the pro-apoptotic protein Hif3a, cleaved parp, caspase 3, and Bax in hippocampal neurons." (PMID 34975464, 2021).
Hypertension (2 papers, 2021 to 2024). The presence of chronic increased pressure in the systemic arterial system. "Two DEGs (Esr1 and Hif3a) encoding transcription factors and associated with hypertension were identified." (PMID 38928385, 2024).
Hypoglycemia (2 papers, 2019 to 2023). A decreased concentration of glucose in the blood. "HIF3A is usually highly expressed in the adipocytes, and the up-regulation of HIF3A is a typical response to hypoglycemia and glucoprivation in vivo." (PMID 31652442, 2019).
ischemic stroke (2 papers, 2021 to 2026). A stroke disorder caused by obstruction of blood flow to the brain, due to thrombotic (local blood clot formation) or embolic (due to a blood clot or other material traveling from another site) event. "This review delineates the intricate mechanisms by which HIF-1α and the less-characterized HIF-3α modulate ferroptosis in ischemic stroke." (PMID 42254662, 2026). "By synthesizing the distinct regulatory networks of HIF-1α and HIF-3α, this review underscores their potential as therapeutic targets and proposes that selective modulation of these pathways could offer novel neuroprotective strategies for ischemic stroke." (PMID 42254662, 2026). "However, there are no reports on the association between HIF-3α genetic variants and ischemic stroke (IS) susceptibility." (PMID 33226577, 2021).
liver diseases (2 papers, 2015 to 2017). "This study provides new evidence to the function of HIF3A gene, which would be helpful for future risk assessment and personalized treatment of liver diseases." (PMID 28754107, 2017). "We haven’t found direct evidences linking HIF3A gene with plasma ALT or liver diseases, but some studies on HIF1A, hypoxia or liver diseases may give some cues." (PMID 26717317, 2015). "The results not only provide new cues on the function of HIF3A methylation, but also provide evidence for identifying epigenetic factors of elivated ALT and may be useful for risk assessment and personalized medicine of liver diseases such as NAFLD." (PMID 26717317, 2015).
thymoma (2 papers, 2022 to 2024). A neoplasm arising from the epithelial cells of the thymus. "In a recent study, HIF3A was also differentially expressed in thymoma patients with MG, pointing to the relationship between hypoxia and TAMG." (PMID 38734662, 2024). "Among the 33 cancer types, ACSL4 expression was most correlated with TMB in ACC, whereas FANCD2, HIF3A, HSPA5, and PSMB7 were most correlated with TMB in thymoma (THYM)." (PMID 35652069, 2022).
adenoma (1 paper, 2015). A neoplasm arising from the epithelium. "To gain insight into the association of several Let-7 targets with tumorigenesis in vivo, we examined Hmga1, Hmga2, Arid3a, and Hif3a protein expression by immunostaining adenomas and adenocarcinomas, as well as adjacent normal tissue, from Lin28bLo/Let7IEC-KO mice." (PMID 26244988, 2015).
anemia (1 paper, 2011). A reduction in the number of red blood cells, the amount of hemoglobin, and/or the volume of packed red blood cells. "Combined with recent evidence in vivo about the role of HIF2α in erythropoiesis, we propose a hypothesis: positive regulation by HIF2α and negative regulation by HIF3α may be necessary for correct renal Epo induction during hypoxia/anemia." (PMID 22022454, 2011). "We, therefore, hypothesized HIF3α-related negative regulation is also necessary in renal Epo production during hypoxia/anemia." (PMID 22022454, 2011).
atherosclerosis (1 paper, 2025). A disease characterized by the build-up of fatty material and calcium deposition in the arterial wall resulting in partial or complete occlusion of the arterial lumen. "In both of these datasets, HIF3A expression in atherosclerosis was confirmed, with a decreased expression both in plaques with IPH and in unstable vs stable plaque regions." (PMID 40034249, 2025). "Although several factors related to hypoxia such as HIF1A and downstream targets of the HIF pathway, such as PDK-1 and VEGF, have been studied in detail in atherosclerosis, HIF3A expression has not previously been reported." (PMID 40034249, 2025).
bladder cancer (1 paper, 2025). "The analysis revealed that UBE2D3 and COPS2 are highly expressed in seven different bladder cancer cell types, whereas HIF3A and CUL1 are expressed at low levels in the same cell clusters." (PMID 40524221, 2025). "Further multivariate Cox regression confirmed that HIF3A, DDB1, COPS2, and UBE2D3 may independently indicate bladder cancer prognosis." (PMID 40524221, 2025).
Burkitt lymphoma (1 paper, 2017). A rare form of malignant mature B-cell non-Hodgkin lymphoma. "A similar analysis of 17 EBV+ endemic Burkitt lymphomas indicated HIF-1α mRNA was, on average, nine-fold more abundant than HIF-2α mRNA (range 2-fold to 19-fold), with HIF-3α mRNA detectable above background in only one of these 17 tumors (at 1/20th of the HIF-1α level)." (PMID 28617871, 2017).
cardiac arrest (1 paper, 2025). Cessation of breathing and/or cardiac function. "Overall, Epsa1, Hif3a, and Idh2 demonstrated significant diagnostic value, suggesting that they could be considered as potential drug targets for diagnosing the regulation of hippocampal neuron mitochondria in rats after heparin-induced cardiac arrest and cardiopulmonary resuscitation." (PMID 41585220, 2025). "To determine the potential value of the three key genes, Epsa1, Idh2, and Hif3a, in regulating the mitochondria of hippocampal neurons in rats after heparin-induced cardiac arrest and cardiopulmonary resuscitation, we conducted a receiver operating characteristic (ROC) analysis." (PMID 41585220, 2025).